LINC01122 (long independently transcribed non-coding RNA 1122)
Synonyms: uc.54; uc.53; uc.52; FLJ30838; AC007092.1; LINC01793
Gene: Long non-coding RNA gene on chromosome 2 (58,427,707 to 59,355,588, forward strand). Ensembl gene ENSG00000233723.
Diseases named in the same sentence as LINC01122 in open-access papers:
LINC01122 is named in the same sentence as 1 disease in open-access papers, as found by Europe PMC text mining. Sharing a sentence is not in itself a finding about the gene and the disease. The quoted sentences say what the papers report.
Obesity (1 paper, 2025). Accumulation of substantial excess body fat. "Another GWAS found that the genes FBN2, LINC01122, and RGS6, which relate to obesity, are also linked to sleep activity in children." (PMID 40024983, 2025).